Y_RNA (Y RNA )
Gene: Miscellaneous RNA gene on chromosome 3 (43,472,477 to 43,472,596, forward strand). Ensembl gene ENSG00000251811.
Homologues: Orthologues: chimpanzee Y_RNA (98% identical), macaque Y_RNA (89% identical). Paralogues in human: Y_RNA (77% identical), Y_RNA (75% identical), RNY1P2 (74% identical), Y_RNA (74% identical), Y_RNA (73% identical), Y_RNA (72% identical), RNY1 (72% identical), RNY1P11 (71% identical), Y_RNA (71% identical), Y_RNA (70% identical), Y_RNA (69% identical), RNY1P4 (68% identical), and 89 more.